BRCA1 (BRCA1 DNA repair associated)
Diseases named in the same sentence as BRCA1 in open-access papers (continued):
Sharing a sentence is not in itself a finding about the gene and the disease.
breast cancer (continued). "Interestingly, while in Belgian and Czech breast cancer patients the frequency of BRCA1 germline PV is higher than BRCA2, BRCA2 PV prevails in PDAC patients in both populations." (PMID 34503238, 2021). "In addition to its crucial role in preventing genomic instability, BRCA1 acts as a co-repressor for Myc target genes, which in the absence of BRCA1, promote the aggressive basal-like phenotype in breast cancer." (PMID 34638302, 2021). "Here, we apply a novel strategy using a case-only GWAS design, in which SNP genotype frequencies in 7,257 BRCA1 and 5,097 BRCA2 mutation carrier BC cases are compared to those in 60,212 BC cases from the Breast Cancer Association Consortium (BCAC), unselected for mutation status." (PMID 33597508, 2021). "While we cannot rule out an effect of RRSO on breast cancer risk for BRCA1 mutation carriers, this effect is unlikely to be as large." (PMID 31948486, 2020). "Furthermore, CDK12 inhibitors reversed de novo and acquired PARPi resistance in BRCA1-mutant breast cancer cells." (PMID 32563252, 2020). "Indeed, we found a significant association between the presence of BRCA1/2 pathogenic mutations and high BRCA pathway levels in 6 different breast cancer datasets." (PMID 32620799, 2020). "Decreased expression of the BRCA1 gene and protein has also been seen in sporadic breast cancer." (PMID 32235451, 2020). "In our study, RFS, OS, and risk of death from TNBC were similar between patients with breast cancer and BRCA1 germline mutation and noncarriers." (PMID 32322271, 2020). "It has been postulated that breast cancer with BRCA1 promoter methylation is more aggressive." (PMID 32856871, 2020). "Because her grandmother had a history of breast cancer, she underwent BRCA1 and BRCA2 testing." (PMID 32455662, 2020). "Therefore genetic testing for BRCA1 mutations along with BRCA2 is highly crucial in order to streamline early detection and hence reduce mortality of breast cancer." (PMID 32063924, 2020). "Later on, a screen for FANCJ mutations in a Korean cohort with BRCA1/2 mutation-negative high-risk breast cancer identified the germline mutation c.1018C>T, giving rise to FANCJ L340F, as likely pathogenic." (PMID 32542039, 2020). "A transgenic study revealed that PKM2 is not essential for BRCA1-deficiency-mediated breast cancer formation." (PMID 33292198, 2020). "Two high-penetrance breast cancer genes, BRCA1 and BRCA2, are thought to be responsible for only 13% of MBC, and multiple genetic factors remain unknown." (PMID 32185139, 2020). "Using G2 MN and G2 chromosomal assays, some studies have reported the lymphocyte of healthy BRCA1/2 mutation carriers (heterozygous genotype) are hypersensitive to invitro ionizing radiation compared to non-carriers without a history of breast cancer." (PMID 33013205, 2020). "Pre-clinical studies have also revealed the potential of PARPi in promoting the death of breast cancer cells lacking mutations in BRCA1 or BRCA2." (PMID 32235451, 2020). "Mutation in BACH1 or in BRCT domain that could disrupt the interaction between BRCA1 and BACH1, affect the HR pathway, delay DNA repair, and finally increase the risk of breast cancer." (PMID 33013205, 2020). "Although risks with estrogen therapy and breast cancer are well known, patients with a familial history or with breast cancer susceptibility genes (BRCA1 and BRCA2) do not have an additional risk with CHC." (PMID 32397460, 2020). "Regarding failure patterns, patients with BRCA1/2-mutated tumors showed a higher incidence of contralateral breast cancer than those with non-mutated tumors (BRCA1/2 non-mutated vs. mutated tumors: 4.9% vs. 26.0%, p < 0.001)." (PMID 33019612, 2020).
breast cancer (continued). "Women with BRCA1/2 germline mutations have a higher incidence of breast cancer than those without these genetic abnormalities." (PMID 32322271, 2020). "Indeed, for BRCA1 and BRCA2, monoallelic LOF variants present in the germline can result in a nearly tenfold increased lifetime risk of developing breast cancer, whereas bi-allelic LOF variants cause Fanconi anemia (FA)." (PMID 33195396, 2020). "Moreover, the nuclear localization of BRCA1 in T47D breast cancer cells is higher than that in the MDA-MB-231 cells." (PMID 33817238, 2020). "Moreover, one early study showed that among BRCA1/BRCA2 mutations carriers, physical exercise and healthy weight were associated with delayed age at breast cancer onset." (PMID 32436147, 2020). "Contralateral breast cancer developed in 26.5% of BRCA1/2 mutation carriers and in 14% of noncarriers." (PMID 32322271, 2020). "Human BRCA1-mutant breast cancer samples also showed high levels of mesenchymal markers." (PMID 32591500, 2020). "The aim of our study is to evaluate, in a larger group of patients, the contribution of germline mutations in BRCA1 and BRCA2 to breast cancer among Jordanian patients with selected high-risk profile as per the National Comprehensive Cancer Network (NCCN) guidelines." (PMID 32733560, 2020). "Centrosome aberration in breast cancer is associated with germline mutation of BRCA1 or BRCA2 and negative BRCA1 expression." (PMID 32722046, 2020). "Among these variants, four recurrent variants (BRCA1 c.3257del, BRCA1 c.4801A>T, BRCA1 c.440del, and BRCA2 c.7409dup) might be considered as the candidate locus in breast cancer screening." (PMID 32879886, 2020). "Hence, BRCA1 and BRCA2 carriers present a risk of 65–80% and 45–85% for developing breast cancer while, for ovarian cancer they present a risk of 37–62% and 11–23% respectively." (PMID 32778078, 2020). "For example, PVs in ATM and BRCA1 were significantly associated with >twofold increased risk for colorectal cancer and PVs in RAD51D and CDKN2A were significantly associated with >twofold increased risk for breast cancer." (PMID 31406321, 2020). "Screening for BRCA1/2 gene mutations in breast and ovarian cancer using NGS technology could avoid a treatment cost of 42 million baht for patients with advanced breast cancer (37 million baht) or advanced ovarian cancer (5 million baht)." (PMID 33338033, 2020). "On the other hand, the results also indicate that precise regulation of BRCA1 functions to avoid DNA repair in the nucleus but activate cell death signals in the cytoplasm might represent an attractive strategy for combined breast cancer therapies." (PMID 32764667, 2020). "BRCA1 is a classical tumour suppressor gene for family breast cancer." (PMID 34803264, 2020). "Patients with BRCA1/2 pathogenic variants were more likely to have a family history of breast cancer and hormone receptor-negative tumors." (PMID 32318955, 2020). "Finally, the majority of BRCA1/2 breast cancers showed a higher rim enhancement, an imaging feature associated with aggressive malignant tumors." (PMID 32727387, 2020). "Interestingly, the Neu, PyMT and BRCA1-null tumors each comprised of cells which corresponded to several intrinsic breast cancer subtypes." (PMID 32840210, 2020). "Besides BRCA1 and BRCA2, it is extremely important to identify new breast cancer susceptibility genes, for the prevention and treatment of FBCs." (PMID 32300589, 2020). "Thus, the detection of BRCA1 is of great significance for the genetic analysis, early diagnosis and clinical treatment of breast cancer." (PMID 32698331, 2020). "Therefore, fertility protection and fertility treatment of healthy carriers of mutations in BRCA1 and BRCA2 as well as of carriers after breast cancer therapy are gaining importance." (PMID 32719921, 2020). "In breast cancer cases, four BRCA1 heterozygotes and 17 BRCA2 heterozygotes were identified." (PMID 32300229, 2020).
breast cancer (continued). "OLA1 with the E168Q variant, which is identified in breast cancer cell lines, fails to bind to the N-terminal region of BRCA1 and rescue OLA1 knockdown-induced centrosome amplification." (PMID 32722046, 2020). "Regarding clinical trials for breast cancer, the OlampiAD phase III study (NCT02000622) demonstrates that olaparib significantly prolongs PFS in patients with metastatic breast cancer and a germline BRCA1/2 mutation compared to standard therapy." (PMID 32122376, 2020). "Knockdown of HELB in BRCA1-deficient mammary tumor cells results in resistance to PARPi, which suggests that BRCA1-independent HR is activated in the absence of HELB." (PMID 32455610, 2020). "Clinical factors associated with BRCA1 pathogenic variants included a family history of breast cancer and hormone receptor status of the tumor, while for BRCA2, the only statistically significant clinical factor was a family history of breast cancer." (PMID 32318955, 2020). "BRCA1/2 negativity was identified without performing the BRCA1/2 gene test with 92.88% accuracy within minutes in high-risk breast cancer patients with this algorithm, and the test associated result waiting stress, time, and money loss were prevented." (PMID 33488844, 2020). "Moreover, the expression of functional BRCA1 protein has been lost to a significantproportion of sporadic breast cancers, indicating that such a mechanism plays a significant role in breast carcinogenesis." (PMID 34803264, 2020). "We compared RFS, OS, risk of breast cancer death, and survival from distant metastases in BRCA1/2 carriers and noncarriers." (PMID 32322271, 2020). "BRCA1 is the biomarker for the early diagnosis of breast cancer." (PMID 32698331, 2020). "Important to note, patients with BRCA1 promoter methylation receiving chemotherapeutic drug treatment show highly improved breast cancer–specific survival compared with unmethylated controls (hazard ratio = 0.10, 95% confidence interval = 0.01 to 0.75, two-sided P = .02)." (PMID 32175521, 2020). "Thus, searching for a new strategy to generate synthetic lethality for the 80% of BRCA1‐proficient TNBC breast cancer patients is urgent." (PMID 33231937, 2020). "The incidence of breast cancer in female BRCA1/2 carriers increases rapidly in early adulthood." (PMID 32655641, 2020). "A notable exception to this bimodal age distribution at diagnosis is medullary carcinoma, a rare early-onset sporadic breast cancer that is linked to ER-negative and triple negative cancers, Basal-like tumor features, and the BRCA1 mutation." (PMID 31535320, 2020). "When BRCA1 induces GADD45A in breast cancer, it may lead to apoptosis through the JNK pathway and interaction with MTK1/MEKK4." (PMID 32013256, 2020). "Recently, a study showed BRCA1 hypermethylation in canine mammary tumors." (PMID 33194754, 2020). "Are BRCA1 gene tumor mutations associated with poor (not living disease-free) breast cancer outcomes?" (PMID 33391340, 2020). "In vitro depletion of BRCA1 results in amplified centrosomes, a phenotype observed in early-stage tumors, including breast cancer, but how might wild type BRCA1 protein control centrosome amplification is unclear." (PMID 32655836, 2020). "In this case, a mutant BRCA1 gene is not sufficient to increase the risk of breast cancer and thus not all women carrying the BRCA1 mutation develop cancer." (PMID 32295293, 2020). "Many bilateral breast cancer patients with increased hereditary susceptibility to breast cancer result negative for BRCA1 or BRCA2 pathogenic variants and, thus, need a further genetic testing through a broader gene panel." (PMID 32854451, 2020).
breast cancer (continued). "Based though on the established inclusion criteria only 10% of female individuals receiving genetic testing due to the early onset breast cancer alone (BC at age < 36 years with negative family history) are expected to carry a BRCA1/2 pathogenic variant." (PMID 32727387, 2020). "Some associations between variability of the GADD45A gene and the occurrence of breast cancer with no BRCA1/2 mutation (sporadic and familial) were found in a large cohort study performed in a Chinese population." (PMID 32013256, 2020). "All patients having BRCA1 mutation were married, multiparous, breast feeding women, had no family history of breast cancer among their first-degree relatives, and had unilateral invasive ductal breast cancers." (PMID 32856854, 2020). "The Breast Cancer Association Consortium (BCAC) and the Consortium of Investigators of Modifiers of BRCA1/2 (CIMBA) have recently performed large-scale genetic fine-mapping of 150 breast cancer susceptibility regions in ~ 217,000 breast cancer cases and controls of European ancestry." (PMID 31910858, 2020). "BRCA1:c.5030_5033del was observed in three unrelated women with breast cancer from Ukraine, all of whom having a family history of cancer (one had a sister with breast cancer and two had mothers with ovarian cancer)." (PMID 32772980, 2020). "Unlike the BRCA1 gene, activation and overexpression rather than mutations of this gene have been shown in numerous cancers (breast cancer and ovarian cancer) (Birnbaum, Sircoulomb & Imbert, 2009)." (PMID 33062421, 2020). "Patients with deleterious mutations in either BRCA1 or BRCA2 have about five times higher risk of breast cancer that those without such mutations." (PMID 33019612, 2020). "A number of studies have reported germline BRCA1/2 mutation rate of approximately 5% in unselected breast cancer patients regardless of ethnicity." (PMID 32091409, 2020). "Protein–protein interaction (PPI), survival analysis and diagnostic value assessment help us identify key genes associated with BRCA1/2 mutations and provide new insights for the specific mechanisms and treatment targets research of BRCA-mutant breast cancer different from other breast cancers." (PMID 31998560, 2020). "Several studies have investigated prognosis among BRCA1/2 mutation carriers and noncarriers, but the prognostic impact on outcomes of breast cancer patients has not been determined." (PMID 32322271, 2020). "Our findings demonstrate that BRCA1 deficiency impairs mitochondrial function and mitophagy through AMP‐activated protein kinase (AMPK)‐mediated mitochondrial fission and induces inflammasome activation, which then promotes metastasis of Brca1 mutant mammary tumor." (PMID 32195105, 2020). "For example, Breast Cancer genes 1 and 2 (BRCA1 and BRAC2, respectively) are necessary for repair of DSBs through the process of HR; and although mutations in these tumor suppressors predispose towards breast and ovarian cancer, these very mutations can be exploited to induce cell death." (PMID 32180937, 2020). "Risk-reducing surgery for individuals with BRCA1/2 variants and breast cancer has not yet demonstrated an overall survival benefit." (PMID 32090079, 2020). "Interestingly, by the other two comparisons, we identified 43 overlapping genes that not only significantly expressed in wild-type breast cancer patients relative to normal tissues, but more significantly expressed in BRCA1/2-mutant breast patients." (PMID 31998560, 2020). "Interestingly, heterozygous mutations in FA genes, i.e., BRCA1/FANCS and BRCA2/FANCD1, confer an increased risk of cancer occurrence, especially breast cancer." (PMID 32300589, 2020). "Many breast cancer cases associated with BRCA1 mutations are classified as TNBC as they do not show the expression of ER, PR and HER2." (PMID 32456160, 2020). "Moreover, we found that both CDKN1B and BRCA1 are targets of miR-575 and regulate miR-575-induced tamoxifen resistance in ER+ breast cancer." (PMID 32929377, 2020).
breast cancer (continued). "Most of the breast cancer cases are sporadic, and in the 10% of the hereditary cancer, BRCA1 and BRCA2 (breast cancer genes 1 and 2) are the best-known susceptibility genes; they are associated with the risk of up to 85% of developing breast cancer in mutation carriers." (PMID 32341648, 2020). "In this study we presented preliminary results showing that imaging texture features extracted from T1 weighted breast MRIs can serve as a predictor allowing for differentiation between high risk breast cancer individuals with or without BRCA1/2 variants." (PMID 32727387, 2020). "Because BRCA1 needs to be translocated into the nucleus to perform its DNA-repairing functions, these results indicated that methylation of BRCA1 by PRMT1 may be necessary to activate BRCA1-dependent DNA repair in breast cancer cells that are subjected to IR." (PMID 32764667, 2020). "On the other hand, BRCA1-type HRD deficiencies were found more often in ovarian and breast cancer." (PMID 33149131, 2020). "MLPA test for BRCA mutation is recommended for breast cancer patients with a familial history of breast and/or ovarian cancer, young breast cancer patients, and patients who test negative for BRCA1/2 small mutations in initial testing." (PMID 32455662, 2020). "Analysis of this study showeddown-regulation of BRCA1 gene, Although it stillneed to evaluate whether BRCA1 mimics similar tasksin mESCs and the breast cancer cells we examined." (PMID 31606974, 2020). "A cohort study has shown improved overall and breast cancer-specific mortality rates in BRCA1 mutation carriers, while for BRCA2, survival rates were not significantly different after a median follow-up for 10.3 years." (PMID 32655641, 2020). "High expression of BRCA1 was related with better survival for the breast cancer patients." (PMID 31763681, 2020). "As previously discussed, DHX9 interacts with BRCA1 to coordinate HR and maintain genomic integrity, however, overexpression of a DHX9 peptide fragment containing the region for BRCA1 interaction was shown to inhibit BRCA1 activity in breast epithelial cells and promote breast cancer progression." (PMID 33437516, 2020). "We describe here a qualitative interview study with women with or without a diagnosis of breast cancer, who tested positive for a BRCA1/2 mutation." (PMID 32812179, 2020). "In this work, electrochemical techniques were used to detect methylation in breast cancer cells, however it is vital to realise that this technology could be applied to alterative gene promoters for the detection of cancer, such as BRCA1 for breast cancer." (PMID 33135722, 2020). "In addition, Peroxisome proliferator-activated receptor gamma (PPARγ) was overexpressed in BRCA1-defective breast cancer patients, and in vascular smooth muscle cells PPARγ was found to regulate PFKP." (PMID 32470015, 2020). "Whether cytosolic BRCA1 controls apoptotic pathways in breast cancer cells by interacting with antiapoptotic proteins such as Bcl-2 is also an issue to be resolved." (PMID 32764667, 2020). "BRCA1 allelic loss also has been found in the most breast cancer cells with or without mutations, and the allelic loss affected BRCA1 transcript expression." (PMID 32235451, 2020). "We described the geographic distribution and relative prevalence of 27 different FANCM PTVs detected in 114 female European breast cancer probands with no pathogenic variants in BRCA1 or BRCA2 genes." (PMID 31991861, 2020).